GAL3ST4 (galactose-3-O-sulfotransferase 4)
Description:
Catalyzes the transfer of a sulfate group from 3'-phosphoadenylyl sulfate (PAPS) to the C-3 hydroxyl group of terminal non-reducing beta-1,3-linked galactose residues, exclusively in O-linked glycoproteins. Participates in galactose sulfation and acts on core 1 (Gal-beta-1,3-GalNAc-R) structures. In vitro, also recognizes Gal-beta-1,3 (GlcNAc-beta-1,6)GalNAc-R, asialofetuin, the Globo H precursor and Gal-beta-1,3(6-O-sulfo)GalNAc-R structures as good substrates.
Synonyms: Gal3ST-4; FLJ12116
Tractability: Antibody: UniProt predicts a signal peptide or a membrane-spanning region.
Gene: Protein-coding gene on chromosome 7 (100,159,244 to 100,168,953, reverse strand). Ensembl gene ENSG00000197093.
Subcellular location: Golgi apparatus, Golgi stack membrane
Subcellular location (Human Protein Atlas): Nucleoplasm; Cytosol
Gene Ontology:
Molecular function: galactose 3-O-sulfotransferase activity; 3'-phosphoadenosine 5'-phosphosulfate binding; proteoglycan sulfotransferase activity; galactosylceramide sulfotransferase activity
Biological process: glycoprotein biosynthetic process; cell-cell signaling; glycoprotein metabolic process; oligosaccharide metabolic process; proteoglycan biosynthetic process; sulfur compound metabolic process; glycolipid biosynthetic process
Cellular component: extracellular exosome; membrane; Golgi cisterna membrane
Genetic constraint (gnomAD): Loss-of-function variants: 35 observed, 36.13 expected, observed/expected ratio (o/e) 0.97, 90% interval 0.74 to 1.28. The upper end of that interval is the gene's LOEUF score, 1.28, which puts it in group 5 of 6, group 1 being the genes least tolerant of losing a copy. Missense variants: 626 observed, 643.44 expected, observed/expected ratio (o/e) 0.97, 90% interval 0.91 to 1.04. Synonymous variants: 246 observed, 264.89 expected, observed/expected ratio (o/e) 0.93, 90% interval 0.84 to 1.03.
Homologues: Orthologues: chimpanzee GAL3ST4 (99% identical), macaque GAL3ST4 (96% identical), dog GAL3ST4 (88% identical), pig GAL3ST4 (87% identical), rabbit GAL3ST4 (82% identical), rat Gal3st4 (79% identical), mouse Gal3st4 (78% identical), tropical clawed frog gal3st4.6 (43% identical), zebrafish gal3st4 (38% identical), tropical clawed frog gal3st4 (35% identical). Paralogues in human: GAL3ST2 (35% identical), GAL3ST1 (30% identical), GAL3ST3 (27% identical).
Diseases named in the same sentence as GAL3ST4 in open-access papers:
GAL3ST4 is named in the same sentence as 4 diseases in open-access papers, as found by Europe PMC text mining. Sharing a sentence is not in itself a finding about the gene and the disease. The quoted sentences say what the papers report.
leprosy (2 papers, 2017 to 2020). Leprosy is a chronic infectious disease affecting primarily the skin and peripheral nervous system. "We suggest the polymorphisms in GAL3ST4 in different population are associated with increased risk of leprosy." (PMID 29180661, 2017). "To assess whether the three kinds of genotype of GAL3ST4 on the susceptibility of leprosy in female patients is exerted through changes in GAL3ST4 expression, we performed an in vitro M. leprae antigen stimulation assay." (PMID 29180661, 2017). "We first reported three new common genetic susceptible loci, one in GAL3ST4 and two in CHGB identified by whole exome sequencing (WES) on four leprosy patients and four healthy relatives from two leprosy families in Henan and Yunnan Province." (PMID 33362202, 2020). "In conclusion, the GAL3ST4 and the CHGB allele variants 23 and 48 are novel genetic loci involved in susceptibility to leprosy among female and male population, respectively." (PMID 29180661, 2017). "Stratified by gender, GAL3ST4 was found to be the susceptible gene only for the female population, and CHGB48 and CHGB23 were susceptibile to leprosy for the male population, respectively)." (PMID 29180661, 2017). "Overall, our study demonstrates a significant association of GAL3ST4 and CHGB polymorphisms with leprosy and suggests that these gene polymorphisms may be a contributing factor in leprosy susceptibility." (PMID 29180661, 2017). "However, three SNP loci (GAL3ST4, CHGB48 and CHGB23) were found to have significant difference in frequency between the leprosy patients and healthy controls from database of 1000 Hapmap project." (PMID 29180661, 2017). "We found that five gene variants including gene GAL3ST4, CHGB48, CHGB23, GLT8D2 and ANKRD35 were more frequently reported than the other ten variants among the remaining six patients from two leprosy families by means of gene sequencing (data not shown)." (PMID 29180661, 2017). "Additionally, our genetic findings combined with the expression of GAL3ST4 and CHGB in PBMC, point strongly to an important function of secretogranin and galactose-3-O-sulfotransferase involved in the synthesis and metabolism of glycoprotein in the study of leprosy pathogenesis." (PMID 29180661, 2017).
tumor (2 papers, 2021 to 2025). "Our TMA study showed that protein expression levels of sulfotransferases Gal3ST4 and CHST1 remained the same in serous ovarian tissue from all tumor stages and degree of differentiation, whereas Gal3ST2 levels were decreased in malignant tissue." (PMID 34555499, 2021).
GAL3ST4 also shares sentences with these, for which no sentence is quoted: diabetes (1 paper); tauopathy (1).